ID2 (inhibitor of DNA binding 2)
Diseases named in the same sentence as ID2 in open-access papers (continued):
Sharing a sentence is not in itself a finding about the gene and the disease.
cancer (continued). "Gut microbial metabolite butyrate can directly modulate antitumor CD8+ T cell response and improve the chemotherapy efficacy through ID2-dependent IL-12 signaling, suggesting that manipulation of gut microbial metabolites could be effective as a part of cancer therapy." (PMID 37201112, 2023). "However, Id2 was reported to play different roles in different cancer cells." (PMID 35982951, 2022). "Although our data fully support the reported binding of Id2 to hypo-phosphorylated Rb, we hypothesize that in anchorage-independent carcinoma cells, formation of the Id2-Rb complex prevents CDK4/6-dependent Rb phosphorylation by retaining or accumulating Rb in its hypo-phosphorylated active form." (PMID 35437308, 2022). "Besides, CDKN2C and ID2 are downregulated while IL6, BIRC3, PLAT, PPARG, and CEBPB are upregulated in three candidate TCM associated with Transcriptional misregulation in the cancer pathway." (PMID 34490085, 2021). "Furthermore, silencing of the ID2 may enhance the ATO-stimulated cell proliferation inhibition in cancer cells." (PMID 30634536, 2019). "ID2 induces the expression of nanog homeobox (NANOG) and sry‐box transcription factor 2 (SOX2), which are cancer stem cell markers, through the PI3K/AKT pathway, and contributes to cell proliferation and cancer stem cell maintenance." (PMID 40448344, 2025). "Recently, we detected that, during the malignization of cancer cells, the opposite effect occurred—the simultaneous extreme upregulation of three ID genes: ID1, ID2, and ID3 (paper in preparation)." (PMID 37372991, 2023). "Genes potentially implicated in carcinogenesis were also discovered on this cholangiocyte trajectory: GSTA3, inhibitor of DNA binding 2, and above all, TMEM45A, a transmembrane molecule from the Golgi apparatus considered as oncogenic in several cancers." (PMID 39130146, 2023). "Seven winning TFs (ETV4, ID2, MEIS1, NR4A3, RARA, TCF3, and ZBTB16) are related to transcriptional misregulation in cancer (p-value: 6.9 × 10−5)." (PMID 36101460, 2022). "Subsequently, seven common genes, including FOSL1, S100A9, CXCL12, ID2, PRS6KA3, AREG, and DUSP6, have been used as the target biomarkers for cancer diagnosis and therapy." (PMID 34490085, 2021). "ID1, ID2 and RUNX2 were also shown to conduce to cancer cell invasiveness, and BAMBI is a BMP target gene implicated in CRC metastasis." (PMID 32326239, 2020). "Pathways related to nervous system development (FDR = 5.8 × 10−8) were enriched for the PID-N genes ASCL1, CTNNB1, ID2, SUFU, and TERT that have known roles in cancer, complementing the PID-C genes NOTCH1, PTEN, and RHOA that also have known cancer roles." (PMID 32024854, 2020). "In this study, we manipulated Id2 expression in poorly invasive MCF-7 and SKOV-3 cancer cells and determined the effects on cell proliferation, in vitro invasion and migration." (PMID 19257909, 2009). "We aimed to reveal the role of Id2 in invasion potential in poorly invasive and estrogen receptor α (ERα)-positive MCF-7 and SKOV-3 cancer cells." (PMID 19257909, 2009). "We aimed to reveal the role of Id2 and its degradation-resistant mutants in cell invasiveness and migration in poorly invasive MCF-7 and SKOV-3 cancer cells positive for ERα." (PMID 19257909, 2009). "In the case of these cancers, and in a subgroup of patients who had received chemotherapy, if the nuclear expression of ID2 was negative, they presented with a better overall survival than those in whom this nuclear expression was positive." (PMID 39130146, 2023). "Consistently, NET cells in state 1 showed a higher expression of cancer stem cell biomarkers (CD44, VGF, and ID2, etc.)and elevated activities of bile acid‐related metabolism and inflammation, whereas state 2 showed enhanced cell proliferation and downregulated cell junction process." (PMID 34185421, 2021).
cancer (continued). "First, we selected the down-regulated genes at PNX0010 under PARG overexpression that are related to cancer development: ID1, ID2, ID3, and SERPINE1 and performed qPCR analysis for 786-O, 769-P, SK-RC-45, and SK-RC-26b cell lines treated with the 10 uM PARP-1 inhibitor rucaparib for 24 h." (PMID 34638458, 2021). "Additionally, association analysis of CMTM6 mRNA levels with Wnt target genes (TCF4, LEF1, CD-44, MMP14, ENC1, ID2, PPARA, and JAG1) from the cancer genome atlas HNSCC cohort using GEPIA showed a positive correlation (r > 0.2)." (PMID 33434185, 2021). "Among the commonly upregulated LD+ associated genes in GBM cells and patient tumors, we found several hypoxia-related, key effectors of angiogenesis, macrophage recruitment and stromal remodeling in cancer (e.g. VEGF-A, TGF-β1, IL1β, ADM, IGFB3, LOX, CA9, THBS1, PLODs, ID2)." (PMID 31174567, 2019). "In contrast to Id1, successful knockdown of Id2 in ACCM cells did not lead to a significant decrease in the proliferation rate or invasion of the cancer cells." (PMID 23517130, 2013). "Moreover, we found that ID2 is a portal vein invasion-related gene in HCV-related HCC and that ID2 negatively regulates the invasive potential of cancer cells." (PMID 23403953, 2013). "In the present study, we observed that Id-2 expression was low in the immortalised oesophageal cell line NE1 and the non-neoplastic oesophageal epithelium samples showed lower Id-2 expression than their cancer counterparts." (PMID 18000500, 2007). "Moreover, ID2 targets two different sets of genes with one involved in mitochondrial activities in SCLC and the other involved in immune response in LUSC, highlighting the importance of the same TF differentially regulated in different cancer subtypes." (PMID 29866045, 2018). "In addition, we found that the BMP targets, ID1 and ID2, were significantly downregulated in the carcinomas, whereas GREM1 and NOG expression increased, albeit not significantly in the case of GREM1." (PMID 27492255, 2016). "The inhibitor of DNA binding and cell differentiation 2 (Id2) is a helix-loop-helix (HLH) protein that acts as negative dominant regulator of basic-HLH transcription factors during development and in cancer." (PMID 29642431, 2018).
infection (18 papers, 2006 to 2025). The state of being infected such as from the introduction of a foreign agent such as serum, vaccine, antigenic substance or organism. "In addition, inhibitor of DNA binding 2 (Id2) was demonstrated to be upregulated in CD8 T cells during infection, and Id2-deficient CD8 T cells were highly susceptible to apoptosis, suggesting that Id2 is an anti-apoptotic gene in CD8 TCM cells." (PMID 33644036, 2020). "The results showed that most pro-inflammatory markers, such as granzyme, Lamp1, Ifng, Prf1, Ccl5, Emoes, and Id2 transcription, increased after infection." (PMID 41459157, 2025). "We observed higher expression of both elncRNAs NONMMUT013718 and NONMMUT024103 as well as their target genes ID2 and Apol10b in the mouse lungs in response to infection." (PMID 30687302, 2018). "Id2 plays an important role in defining the differentiation fate of peripheral lymphocytes and in their responses to infection." (PMID 21437223, 2011). "However, even the CD4i and ID2-reactive Ab titers in this animal were demonstrated to be lower than those elicited in PWH at similar post-infection timepoints." (PMID 40192306, 2025). "Deletion of Id2 in CD8+ T cells resulted in diminished clearance of Listeria after infection." (PMID 38287103, 2024). "Notably, the TF Id2 previously reported to be necessary for Th1 cell generation during infection was reduced in T cells co-cultured with GSK761-treated DCs." (PMID 37232738, 2023). "We examined the expression of hallmarks of BMP signaling during mycobacterial infection and found transcript levels of Bmp2, Bmp4, Bmpr2, and Id2 were consistently upregulated upon infection of mouse peritoneal macrophages with Mtb H37Ra as well as virulent Mtb H37Rv." (PMID 29449840, 2018). "However, co-infection of active Akt with AAV2-Id2-WT significantly enhanced the length and numbers of regenerating axons, suggesting that Id2 functions downstream of Akt, to control axon regrowth." (PMID 27938661, 2016). "Notably, Id2-S14D infection of the damaged brain slice substantially promoted axon regrowth at an even higher rate than that in the Id2-WT." (PMID 27938661, 2016). "The results indicate that there were only two scenarios in which the mutant strain could invade the original strain (i.e., Iu2+Id2>Iu1+Id1): when the transmission rate was high and the infection period was long, or when the transmission rate and the virus mutation rate were high." (PMID 37624336, 2023). "Moreover, Id2 is up-regulated in CD8+ T-cells as well as in memory CD8+ T-cells during infection, whereas Id2-deficient CD8+ T-cells show altered expression of genes influencing survival as well as impaired memory formation in response to infection." (PMID 28122577, 2017). "Id2 expression is low in naïve CD8+ T cells, but it is markedly upregulated in antigen-specific T cells following infection in vivo." (PMID 21437223, 2011). "Our work shed light on the impact of EBV infection by demonstrating strong downregulation of ID2 and ID4 upon infection." (PMID 21194482, 2010). "Without reintroduction of Id2, infection with active Akt expressing adenovirus of the injured region was insufficient to promote notable regrowth of axons." (PMID 27938661, 2016). "In this context, an intriguing finding of the present study is the up-regulation of elncRNA NONMMUT013718 and Id2 during R. conorii infection of RAW264.7 macrophages, whereas only endothelial cells exhibit induced expression of NONMMUT024103 and Apol10b in response to infection." (PMID 30687302, 2018).
adenocarcinoma (5 papers, 2013 to 2024). A common cancer characterized by the presence of malignant glandular cells. "It is therefore conceivable that Id2 is involved in the proliferation of adenocarcinoma epithelium beyond the stage examined here." (PMID 26163528, 2015). "However, ID2 and ID4 mRNA expression levels showed a favorable association with OS in adenocarcinoma." (PMID 32003423, 2020). "However, we could not observe such an induction of Hey1, Hey2 or Id2 in primary human vascular smooth muscle cells from the umbilical artery, HEK293, HeLa or A549 adenocarcinoma cells.This indicates that endothelial cells react much stronger to BMPs in the serum than other cell types and cell lines." (PMID 25799559, 2015).
neurodegenerative disease (3 papers, 2021 to 2025). A disorder of the central nervous system characterized by gradual and progressive loss of neural tissue and neurologic function. "LEF1-associated target genes related to neurodegenerative diseases, such as EGR1, RHOB, and ID2, exhibit binding peaks." (PMID 40918098, 2025).
hematologic malignancies (2 papers, 2009 to 2024). "Given its substrate targets (e.g. BAF155 and RUNX1) and gene targets (e.g. BMI-1 and ID2), CARM1 and phospho-CARM1 appear to play a pivotal role in hematologic malignancies with the JAK2-V617F mutation, and likely in other settings as well." (PMID 38649367, 2024).
metabolic disease (2 papers, 2013 to 2016). A congenital disorder (due to inherited enzyme abnormality) or acquired (due to failure of a metabolically important organ) disorder resulting from an abnormal metabolic process. "In conclusion, our finding that ID2 contributes to the regulation of body temperature and energy homeostasis presents the possibility that ID2 could be a potential therapeutic target for metabolic disease." (PMID 27144179, 2016).
cardiovascular diseases (1 paper, 2012). "Id2 has been linked to the development of cardiovascular diseases since thiazolidinediones, antidiabetic agents and peroxisome proliferator-activated receptor (PPAR) gamma agonists, have been reported to diminish Id2 expression in human cells." (PMID 22701468, 2012).
respiratory diseases (1 paper, 2023). "For example, genes associated with respiratory diseases and cell proliferation (CA5B, ID2, CARD14 and TRIM29) were significantly altered." (PMID 36673815, 2023).
ID2 also shares sentences with these, for which no sentence is quoted: multiple myeloma (3 papers); cervical cancer (2); colorectal (2); ductal carcinoma in situ (2); leukocytosis (2); myeloproliferative disorder (2); neuroendocrine carcinoma (2); acute lymphoblastic leukemia (1); Alzheimer disease (1); autoimmune uveitis (1); B-cell lymphomas (1); Burkitt lymphoma (1); carcinoid (1); cardiac diseases (1); cardiac hypertrophy (1); cholangiocarcinoma (1); chronic myeloid leukemia (1); colon adenocarcinoma (1); colonic carcinoma (1); colorectal adenocarcinoma (1); colorectal tumors (1); dry age related macular degeneration (1); endometrium cancer (1); endotoxemia (1); epilepsy (1); epilepsy syndrome (1); focal epilepsy (1); glomerulosclerosis (1); infectious disease (1); invasive lobular breast carcinoma (1).
A further 33 diseases each share a sentence with ID2 in 1 paper.